CD4 (CD4 molecule)
Diseases named in the same sentence as CD4 in open-access papers (continued):
Sharing a sentence is not in itself a finding about the gene and the disease.
tumor (continued). "In addition, CD4+FOXP3+ regulatory T cells activated the CD39/ENTPD1 pathway and promoted hepatic metastatic tumor growth in mice." (PMID 36185217, 2022). "In addition to effector T cells, macrophages, and NK cells, immunosuppressive CD4+FoxP3+ Treg cells (Tregs), and myeloid-derived suppressor cells (MDSC) also promote tumor growth and progression." (PMID 36437919, 2022). "Expressed on CD8+ T, NK, and CD4+ T cells, CXCR6 could promote the recruitment of tumor-infiltrating lymphocytes in combination with CXCL16 expressed by tumor cells, thus contributing to a better prognosis for cancer patients." (PMID 35978426, 2022). "Because the full assembly of immune components for CD4+ and CD8+ activation are found within LNs, our results demonstrating how lymphatic delivery of CBIs improve anti-tumor responses are consistent with classical teachings on the role of LNs in adaptive immunity." (PMID 35406595, 2022). "Finally, it induced the release of DAMPs by 4T1 cells and the subsequent activation of M1 macrophages, DCs and CD4+ and CD8+ T cells in the tumor tissue and stimulation of the antitumor immune response." (PMID 35335881, 2022). "A former study found that the proportion of immune subsets of peripheral blood lymphocytes may be abnormal in NSCLC patients, of whom the peripheral blood CD8+ cells increased, CD4+ cells decreased, CD4+/CD8+ decreased, and tumor cells occurred immune escape." (PMID 36118825, 2022). "The onlythree patients who were positive for PD-L1 expression were also positive for T CD8+ infiltration and negative for T CD4+ infiltration, which suggests a connection between an ongoing immune response with the tumor cell immune evasion mechanisms." (PMID 35329826, 2022). "Moreover, the distribution of CD4+ T cells and CD8+ T cells in tumor tissues was also checked to assess the immune response after combinatorial OncoAd and PD‐1 mAb therapy." (PMID 35762456, 2022). "Despite the proposed antiangiogenic mechanisms mediated by CD4+ T cells, the inhibition of tumor angiogenesis by itself is not likely to lead to complete tumor rejection in humans, especially in large and already well-vascularized tumors." (PMID 36159781, 2022). "Its high expression in LIHC patients promotes immune cell infiltration in the tumor microenvironment characterized by B cells, CD8+ T cells, CD4+ T cells, macrophages, neutrophils, and dendritic cells with M2 macrophage significant association for a poor survival prognosis." (PMID 36361587, 2022). "With the aid of TIMER2.0 resource, we employed the EPIC, TIMER, QUANTISEQ, XCELL, CIBERSORT, CIBERSORT-ABS methods to analyze the correlation between the infiltration levels of CD4+ T cell subtypes and the mRNA expression of LMNB1 across different TCGA tumor kinds." (PMID 35241075, 2022). "Together, these results suggest that tumor cell GILT expression significantly impacts Ag processing and CD4+ T cell recognition, and may contribute to the future designing of cancer vaccines." (PMID 35162988, 2022). "Such a carrier was then able to induce specific antibody responses in mice and CD4+ and CD8+ T cell proliferation within the tumor, the spleen, and inguinal lymph nodes, resulting in a very effective tumor immunity therapeutic (i.e., 10-fold tumor size reduction after 24 days)." (PMID 36365144, 2022). "Based on this, authors recently demonstrated in NSG mice that CD4+ CD26hi CAR-T cells mediate durable and relapse-free immunity while bulk CD4+, Th1, Th2 or Th17 cell therapies elicited only transient delays in human tumor growth." (PMID 35008422, 2022). "Interactions between DC-expressing molecules (major histocompatibility complex (MHC) proteins loaded with tumor antigens and costimulatory molecules (CD80, CD86)) with T cell-expressing receptor (TCR), coreceptors (CD4, CD8), and CD28 are necessary for optimal activation of T lymphocytes." (PMID 35757015, 2022).
tumor (continued). "However, in contrast to CD4+ Tconv, the profile of Tregs is quite unchanged in TLS and non-TLS areas, suggesting similar effector functions in each sub-areas of the tumor." (PMID 36566320, 2022). "However, TGF-β2 blockade in combination with PD-1 inhibition significantly downregulated the ratio of Tregs to CTLs, and CD4+ cells to CD8+ cells, at the tumor site." (PMID 36358638, 2022). "Overall, our results suggest that companionship between exhausted tumor-Ag-specific CD4 and CD8 T cells could apply in the periphery as well as at the tumor site." (PMID 35954341, 2022). "To explore the correlation between EPOR gene expression and immune infiltration, we first analyzed the correlation of EPOR with six infiltrating immune cells (B cells, CD4 + T cells, CD8 + T cells, macrophages, neutrophils, and dendritic cells) and tumor purity in the TIMER2.0 database." (PMID 35359375, 2022). "Previous studies have claimed that infiltration of TCF1+CD8+ T cells contributes to the induction of tumor regression but not that of TCF1+CD4+ T cells." (PMID 36211334, 2022). "Since tumor-reactive CD4+ and CD8+ T cells both secrete CXCL13, it is likely that this chemokine plays a key role in controlling the recruitment of immune cells to the TME as well as in the spatial organization of the immune cell infiltrate within the tumor." (PMID 35439168, 2022). "Tumor infiltrating lymphocytes (TILs), commonly recognized as an immunological parameter and a morphological manifestation of anticancer immune response, represent a major infiltrating immune cell subpopulation, which consist of CD3+, CD4+, and CD8+ TILs." (PMID 35433455, 2022). "Flow cytometry data demonstrated the pronounced increase in the percentage of CD69+ cells in both CD4+ Th (p < 0.002) and CD8+ T-cells (p < 0.002) and moderate increase in the percentage of CD25+ among CD4+ Th cells (p < 0.03) in all tumor-bearing mice in comparison with “Control” group." (PMID 36555468, 2022). "Importantly, the tumor size and frequency of IFN-γ–producing CD8+ T cells in tumors were similar between the recipients of DKO CD8+ T cells plus WT CD4+ T cells and the recipients of Pten-KO CD8+ T cells plus WT CD4+ T cells." (PMID 35143421, 2022). "By analyzing the tumor-infiltrating immune cells predicted by the CIBERSORT algorithm, we found that among the 9 differentially infiltrating immune cells, only T cells CD4 memory activated, T cells follicular helper and NK cells resting were highly infiltrated in the low-risk group." (PMID 36526698, 2022). "NDMI score, but not DEX use at blood draw or neutrophil proportion, remained a significant predictor of survival time in a final model that included age, surgery, tumor location, WHO subtype, body mass index, CD4 T cell proportion, and an interaction between WHO subtype and NDMI score." (PMID 36127421, 2022). "Interrogating the bimodal separation of activated CD4 T cells and their negative correlation with tumor burden identified responders and non-responders of the ITI-1001 treatment group." (PMID 35651802, 2022). "Thus far, the data show that the DP CD4+ Th TILs are highly activated and proliferating in the TME, suggesting recognition of their cognate antigen in the tumor." (PMID 35439168, 2022). "Treatment with Protein vaccine alone increased tumor infiltration of CD8+ T cells but not CD4+ T cells (p=0.1892)." (PMID 36341387, 2022). "Interestingly, the proportions of CD4+ and CD8+ T-cells in the tumor tissues were significantly higher in the combination therapy group than in the ADM monotherapy group." (PMID 35818037, 2022). "A notable increase in CD4+ and CD8+ T cells in the tumors treated with Rg3-Lp/DTX could be observed, indicating that tumor immunity was getting hotter." (PMID 36109762, 2022). "Therefore, immune profiles including CD3, CD4, CD8, and PD-L1 have been increasingly studied so as to gain a deeper understanding of the tumor microenvironment." (PMID 36528658, 2022).
tumor (continued). "As supported in another high-dimensional profiling study of CD4+ TILs in human cancer tissues, CD39 expression could be used to distinguish tumor-specific CD4+ T cells from diverse CD4+ TILs (e.g., regulatory T cells and bystander CD4+ T cells)." (PMID 36451828, 2022). "Here, we first analyzed the relationship between FCGR3A expression and the infiltration levels of six common immune cells (B cells, CD4+T cells, CD8+T cells, DC cells, macrophages, and neutrophils), and observed a positive correlation in the vast majority of tumor types." (PMID 35668930, 2022). "However, the mRNA level of STEAP3 was negatively correlated with tumor purity and the infiltration of CD8+ T cell, macrophage and dendritic cell, but positively correlated with CD4+ T cell and neutrophil." (PMID 36229881, 2022). "The frequencies of FoxP3−Helios− T cells and CD4+CTLA-4+ T cells in PBMCs were found to have stronger negative correlations in advanced tumor stages, compared to early stages (r = −0.041, p = 0.903 [early]; r = −0.651, p = 0.003 [advanced])." (PMID 36146549, 2022). "CD8+ T cells co-cultured with NDV-preinfected tumor cells in the presence of SEB showed significantly greater proliferation and IFN-γ production than those cultured with untreated tumor cells; CD4+ T cells similarly increased their TNF and IFN-γ production." (PMID 36418317, 2022). "Both anti CD4 and anti CD8 abolished anti-tumor activity induced by αCTLA-4/C20-IM." (PMID 35110563, 2022). "Furthermore, we performed WB and immunofluorescence to investigate the expression and distribution of CD3+, CD4+ and CD8+ T cells in the tumour and para-tumour tissues." (PMID 35530333, 2022). "Analysis of tumor-isolated leukocytes revealed a significant increase in CD8+ T cells with increased IFNγ and granzyme B expression as well as decreases in CD206+ F4/80+ macrophages, Gr1+ CD11b+ MDSCs, and CD25+ CD4+ Tregs." (PMID 35736351, 2022). "Moreover, the population of CD3+CD4+T cells, NK cells, and CD3+CD8+T cells was significantly increased in the tumor tissue of the hPRDX5 group, while the proportion of granulocytic-myeloid-derived suppressor cells decreased slightly." (PMID 36102418, 2022). "The presence of Treg in TLS may negatively affect the levels of activation and infiltration of CD4+ and CD8 + T cells, resulting in tumor escape from immune surveillance." (PMID 36082777, 2022). "Consequently, GLP enriched the population of CD4+ and CD8+ T cells and enhanced the production of type 1 T helper (Th1)-type cytokines (IFN-γ and IL-12) in the spleen of tumor-bearing mice." (PMID 35865946, 2022). "Dividing the population according to their progression after 16 weeks, the elevation of IL-10 in the blood samples correlated with a higher CD4/CD8 ratio in tumor and non-tumor tissues and a poor prognosis." (PMID 36230554, 2022). "Only the percentage of intratumoral CD8+ Teffs (CD8+CD25+) and CD4+ Teffs in the tumor and drained lymph nodes (CD25+FoxP3−), but not that of the circulating Teffs, was significantly decreased." (PMID 35955841, 2022). "CD4+ T cells have been shown to initiate a strong antitumor response in tumors by enhancing the clonal expansion of cytotoxic T lymphocytes as well as directly through the secretion of TNF-α and other tumor-suppressive factors." (PMID 35565302, 2022). "The targeting of diverse antigens to Treml4+ cDC1 by anti-Treml4 antibodies elicited both CD4+ and CD8+ T cell responses, but the effects of antigen delivery on disease severity in various models, including tumor transplantation and EAE, remain to be more fully elucidated." (PMID 35225867, 2022). "Tumor-infiltrating T cells are populations containing many different subsets of cells, which can be divided into different subsets according to different differentiated antigens, including 5 types, namely, CD3+, CD4+, CD8+, CD16+, and CD25+." (PMID 36124030, 2022).
tumor (continued). "Among them, TILs may interact with TAMs, for example, the CD4 T cell-secreted IL4 may be involved in the M1-M2 transition, thereby facilitating tumor escape." (PMID 35574386, 2022). "Most of the immune cell members were significantly enriched in the normal samples rather than in tumor samples, except the activate B cell, CD56dim natural killer cell, and activate CD4 T cell." (PMID 35359451, 2022). "It was demonstrated that LDHA could prevent the infiltration of antitumor immune cells (CD4+/CD8+ T cells) and enhance the accumulation of the protumoral immune cells (bone marrow-derived immunosuppressive cells and TAMs) in the tumor microenvironment (TME)." (PMID 36230479, 2022). "Similar to the effect on tumor Ag-specific T cell cross-priming, activation of CD8+ and CD4+ T cells, as well as Ly6c+ Th1 effector cells, were completely abrogated, indicating that type I IFN signaling also is a main inducer of early T cell activation upon NDV infection." (PMID 36418317, 2022). "Remarkably, tumor-treated SC significantly suppressed the inducible proliferation of CD8+ and CD4+ T cells up to five folds, suggesting their functional impairment, which may be associated with the exhausted phenotype." (PMID 36428970, 2022). "While stimulator of interferon genes (STING) activation in innate immune cells of the tumor microenvironment can result in CD8 T cell-dependent antitumor immunity, whether STING signaling affects CD4 T-cell responses remains elusive." (PMID 35091453, 2022). "Because CD4+ Th1 cells are characterized by the secretion of IFN-γ, the isolated CD4+ T cells were incubated with B16F10 tumor cells in vitro in the presence of isotype or anti-IFN-γ antibody for 24 hours, and the viability of B16F10 cells was assessed by using CCK-8." (PMID 35874660, 2022). "However, a clear increase in the percentage of infiltrating CD4+ and CD8+ T cells was detected in SMGs of tumor-bearing Atg5flox/flox mice at Day 25 by IHC." (PMID 35966597, 2022). "The tumor markers (vascular endothelial growth factor (VEGF), carcino-embryonic antigen (CEA), and squamous cell carcinoma antigen (SCC-AG)) and T lymphocyte subsets (CD3+, CD4+, CD8+, and CD4+/CD8+) were determined before and after treatment." (PMID 36276277, 2022). "Indeed, CR was found to lower the number of tumor-promoting immune cells (CD11b+Gr1+) and to increase tumor-fighting (CD8+ and CD4+) immune cells." (PMID 35897685, 2022). "Moreover, the proportions of total CD4+ T cells residing in the resting/neutral state versus the activated state was significantly different in the GC and LAIT‐treated tumours compared to that in the CTRL and PTT‐treated tumours." (PMID 35808806, 2022). "In addition, TRCs in tumor dLNs restrain the expression of CCL21 and IL-7, thus limiting CD4+ T cell priming." (PMID 36700220, 2022). "In vivo, preclinical syngeneic models of colorectal cancer have demonstrated that micrometastatic tumor deposits feature activated CD4+ and CD8+ T cells that are not present in macroscopic tumors." (PMID 36382087, 2022). "CD4+ T-cells induced against the three immunogenic epitopes were able to recognize MHC-II-positive Capan-1, indicating the presentation of those epitopes on the tumor cell surface." (PMID 35655709, 2022). "Finally, TIMER and GEPIA analysis verified that ZNF320 expression is closely related to tumor infiltrating immune cells (TIIC), including B cells, CD8+ T cells, CD4+ T cells, macrophages, neutrophils, and dendritic cells." (PMID 36287187, 2022). "In comparison GSVA bar plots comparing the activities of 50 hallmarks between tumor-derived and nonmalignant tissue-derived CD4+ and CD8+ T cells." (PMID 36506053, 2022). "However, compared to tumor samples, NAU samples had significantly less abundance of activated CD4+ cells (p = 5.28 × 10−3), macrophages (p = 16.8 × 10−5), activated dendritic cells (p = 0.0002), and activated NK cells (p = 0.015)." (PMID 35626146, 2022).
tumor (continued). "Upregulated glycolytic level in both CD4+ T and CD8+ T cells can activate branching pathways such as PPP and serine-one carbon pathway to generate enough intermediates to support biosynthesis and their anti-tumor functions." (PMID 36319992, 2022). "In support of that, we showed that, contrarily to terminally exhausted CD8 T cells, tumor-infiltrating exhausted CD4 T cells expressed only CD69, but no other Trm markers." (PMID 35954341, 2022). "The immune response through the TME is achieved with CD4+ T cells, CD8+ T cells and NK cells, which are directly suppressed not only by tumor cells but also by immunosuppressive Tregs, immature dendritic cells (DCs), tumor associated macrophages (TAMs) and myeloid derived suppressor cells (MDSCs)." (PMID 35957909, 2022). "The results showed that the H-XRT + α-TIGIT + α-PD1 group was capable of increasing the percentages of total CD4+ T-cells, CD4+ Foxp3+ Tregs, as well as total CD8+ T-cells at the unirradiated secondary tumor site compared to the Ctrl group (p = 0.05, p = 0.0251, p = 0.0111, respectively)." (PMID 35008385, 2022). "Despite the fact that UA-liposomes are only able to slow down tumor growth without completely destroying tumor tissue, an in vivo administration of these liposomes led to a depletion of MDSCs and CD4+CD25+Foxp3+ Tregs in the TME." (PMID 35335881, 2022). "Moreover, arginine supplementation promoted the accumulation of activated macrophages, mature DCs, as well as activated CD4+ and CD8+ T cells, which resulted in the inhibition of tumor growth and enhanced survival of mice." (PMID 36713558, 2022). "Heterogeneity in the immunohistochemical assessment for PD-L1 and TILs (CD4 and CD8) expression both within and between tumor sites is a well-documented phenomenon that could have important implications, especially for PD-L1 accuracy as a predictive biomarker." (PMID 34009410, 2022). "A significant anti-tumor effect was observed in the irradiated and abscopal tumors, thus we next examined the immune microenvironment including CTL (CD8+, Granzyme B+ (GzmB+) in CD45+) and Treg (CD4+, FoxP3+ in CD45+)." (PMID 35565217, 2022). "Conversely, pre-existing immunity to OVs via the formation of immune complexes could trigger MHC-II presentation leading to tumor colonization of pre-existing cytotoxic T cells (i.e., CD8+ T cells, CD4+ T cells, etc.), amplifying their antitumor activity." (PMID 36457491, 2022). "Consistently, B cells not only induce a non-protective humoral immune response, but also inhibit CD4+ T cells to mount CTL-mediated tumor immunity." (PMID 36249034, 2022). "Moreover, the examination results of immunohistochemical (IHC) staining of CD3+, CD4+, and CD8+ T cells in the tumor tissues were consistent with those of above flow cytometry analyses." (PMID 35847556, 2022). "Here, we found that the tumor growth of Smad4 WT PDAC cells in vivo was not affected by the depletion of immune cells including CD4+, CD8+ T cells or NK cells, suggesting poor immunogenicity of the PDAC tumor cells." (PMID 35064757, 2022). "In contrast, depletion of CD4+ T cells did not influence the anti-tumor effect of L. paracasei sh2020." (PMID 35259052, 2022). "On the other hand, another study reported that β-catenin pathway activity in murine T CD4+ cells leads to increased RAR-related orphan receptor C (RARC) regulation and Th17 cell differentiation, thus resulting in the secretion of tumor-induced pro-inflammatory cytokines." (PMID 37305016, 2022). "Bevacizumab may normalize the aberrant vascular‐immune crosstalk by reorganization of malformed tumor vessels to improve the infiltration of CD8+ T and CD4+ TH1 cells into the TME." (PMID 34309225, 2022). "Thus, we analyzed the distribution of CD4+ and CD8+ T cells in tumor tissues excised from CT26-HER2/neu–TBM on day 23 after three treatments with HCT-mono-mIL12." (PMID 36405748, 2022).